CXCL6 (C-X-C motif chemokine ligand 6)
Diseases named in the same sentence as CXCL6 in open-access papers (continued):
Sharing a sentence is not in itself a finding about the gene and the disease.
periodontitis (9 papers, 2022 to 2025). An acute or chronic inflammatory process that affects the tissues that surround and support the teeth. "Overall, the findings demonstrate that COL4A2, CYR61, and CXCL6 have strong diagnostic potential, highlighting their utility as biomarkers for periodontitis." (PMID 40539067, 2025). "Comprehensive bioinformatics analysis identified COL4A2, CYR61, and CXCL6 as key genes associated with oxidative stress in periodontitis." (PMID 40539067, 2025). "The results showed significant causal relationships between CD93, CD69, and CXCL6 and periodontitis." (PMID 39717623, 2024). "The findings suggest that CD93, CD69, and CXCL6 are closely related to the progression of periodontitis, with MR confirming their causal links to the disease." (PMID 39717623, 2024). "In conclusion, we found that CXCL5 and CXCL6 are closely associated with the occurrence of periodontitis." (PMID 38168591, 2024). "In conclusion, we integrated multiple bioinformatics analyses and found that CXCL5 and CXCL6 are closely associated with the occurrence of periodontitis." (PMID 38168591, 2024). "The results showed that CD93, CD69, and CXCL6 were all significantly causally associated with the occurrence of periodontitis." (PMID 39717623, 2024). "Our present pilot study suggests that CXCL5 and CXCL6 have the potential to be used as a diagnostic biomarker of periodontitis." (PMID 38168591, 2024). "Specifically, we identified two genes, COL4A2 and CXCL6, which are closely associated with oxidative stress and may play a critical role in the pathogenesis of periodontitis." (PMID 40539067, 2025). "MR confirmed significant causal relationships between CD93, CD69, and CXCL6 and periodontitis." (PMID 39717623, 2024). "COL4A2 and CXCL6 were identified as potential therapeutic targets for the treatment of periodontitis." (PMID 40539067, 2025). "In the context of periodontitis, CXCL6 expression is markedly elevated in the gingival tissues of patients, where it is closely associated with inflammatory cell infiltration and tissue damage." (PMID 40539067, 2025). "Among these genes, COL4A2 and CXCL6 showed elevated expression levels in the gingival tissues of periodontitis rats." (PMID 40539067, 2025). "The results confirmed that the expression levels of COL4A2, CYR61, and CXCL6 were significantly different between periodontitis patients and the control population (P < 0.05)." (PMID 40539067, 2025). "We compared the gene expression level using immunohistochemical, and found that the IOD/Area score of CXCL5 and CXCL6 in periodontitis patients were significantly higher than those in health controls (p < 0.01)." (PMID 38168591, 2024). "Research has shown that, in addition to being considerably elevated in individuals with inflammatory bowel disease, CXCL6 is also expressed more highly in those who have periodontitis." (PMID 38882664, 2024). "We conducted a detailed analysis of the expression levels of CD93, CD69, and CXCL6 in normal and periodontitis tissues, revealing that all three genes were significantly upregulated in periodontitis tissues." (PMID 39717623, 2024). "The expression levels of CXCL5 and CXCL6 were significantly higher in periodontitis patients compared to those in controls." (PMID 38168591, 2024). "Our MR analysis, using eQTL and pQTL data, identified significant causal relationships between periodontitis and the genes CD93, CD69, and CXCL6." (PMID 39717623, 2024). "To explore the connections between CD93, CD69, and CXCL6 and periodontitis, we performed single-cell data analysis." (PMID 39717623, 2024). "Both the in-silico analysis and the experimental results showed that CXCl6 is involved in the development of periodontitis." (PMID 38168591, 2024). "The results of the PPI analysis indicated that CXCL5 and CXCL6 are key genes involved in the development of periodontitis." (PMID 38168591, 2024).
periodontitis (continued). "Our scRNA-seq analysis revealed that macrophages expressed Ccl2, Ccl9, Cxcl4, and Cxcl6, and neutrophils expressed Ccl3, Ccl4, Ccl6, Cxcl2, and Cxcl3 throughout periodontitis development." (PMID 38015204, 2023). "Dysregulated CXCL6 expression has been detected in cases of inflammatory bowel disease and periodontitis." (PMID 37509721, 2023). "Additionally, qPCR analysis confirmed the upregulated expression of COL4A2 and CXCL6 in gingival tissues of periodontitis-induced rats." (PMID 40539067, 2025). "Studies have demonstrated that CXCL6 acts synergistically with IL-8 to enhance the inflammatory response by promoting neutrophil chemotaxis, thereby driving the pathological progression of periodontitis." (PMID 40539067, 2025). "CXCL6, essential for neutrophil chemotaxis, highlights the dual role of neutrophils in both controlling bacterial infection and contributing to tissue destruction in periodontitis." (PMID 39717623, 2024). "ROC curve analysis showed that the AUROC values for CXCL5 and CXCL6 were 0.834 and 0.82, respectively, indicating that they might have excellent specificity and sensitivity for the diagnosis of periodontitis." (PMID 38168591, 2024). "Currently, there is limited research on CXCL5 and CXCL6 as biomarkers for periodontitis." (PMID 38168591, 2024). "This suggests that CD93, CD69, and CXCL6 are not only involved in the immune responses driving periodontitis but may also serve as promising therapeutic targets." (PMID 39717623, 2024). "Further research is crucial to determine whether CXCL5 and CXCL6 can serve as predictive biomarkers for the diagnosis and treatment of periodontitis." (PMID 38168591, 2024). "Our study suggests that they might have predictive potential, and combining CXCL5 and CXCL6 with other biomarkers may enhance the ability to predict periodontitis." (PMID 38168591, 2024). "The PPI network analysis revealed that C-X-C motif chemokine ligand 5 (CXCL5) and C-X-C motif chemokine ligand 6 (CXCL6) could play an important role in the process of periodontitis." (PMID 38168591, 2024). "Additionally, while we identified a correlation between oxidative stress activity and the expression of COL4A2 and CXCL6, the precise mechanisms by which these genes influence oxidative stress and contribute to the progression of periodontitis remain unclear." (PMID 40539067, 2025). "However, the relationship between CXCL5 and CXCL6 and periodontitis is not yet fully understood." (PMID 38168591, 2024). "Our findings enhance personalized medicine strategies for periodontitis by identifying key biomarkers CD93, CD69, and CXCL6 and their links to the disease through MR." (PMID 39717623, 2024). "The enrichment of TNFRSF21+ fibroblasts with high expression of CXCL1, CXCL2, CXCL5, CXCL6, CXCL13, and IL24 was detected in patients with periodontitis compared to healthy individuals." (PMID 35154475, 2022). "Additionally, to further explore the specific roles of these key genes in the pathological process of periodontitis, we analyzed the cell-type-specific expression patterns of CD93, CD69, and CXCL6 using single-cell RNA sequencing." (PMID 39717623, 2024).
colon carcinoma (8 papers, 2007 to 2023). "It is widely acknowledged that CXCL6 promotes the growth and metastasis of various cancers, including non-small cell lung cancer, colon cancer, and melanoma." (PMID 30984000, 2019). "CXCL6, as another chemokine family member, also plays an important role in tumor proliferation and metastasis in various cancer, including non-small cell lung cancer and colon cancer." (PMID 35432485, 2022). "CXCL6 and CXCL12 promoted the metastasis of colon carcinoma by cooperatively activating the PI3K/Akt/mTOR pathway." (PMID 37491836, 2023). "For instance, CXCL6 secretion is increased by fibroblast-derived CXCL12/SDF-1α, which also enhances colonic cancer metastatic potential through the PI3K/Akt/mTOR pathway." (PMID 30237403, 2018). "Patients with anastomotic leakage could have an upregulated inflammatory response before surgery, as expressed by elevated serological levels of CXCL6 and CCL11 for rectal cancer and hs-CRP levels in patients with colonic cancer respectively." (PMID 35652588, 2022).
colorectal cancer (8 papers, 2017 to 2025). A primary or metastatic malignant neoplasm that affects the colon or rectum. "In cancer, CXCL6 is often upregulated, and its expression is associated with poor prognosis in various malignancies, including colorectal cancer, gastric cancer, and others." (PMID 39741907, 2024). "CXCL12 derived from stromal cells in the tumor microenvironment depends on PI3K/Akt/mTOR signal to up-regulate the secretion of CXCL6 or down-regulate the expression of PTEN through PI3k/Akt signal to enhance the liver metastasis of colorectal cancer." (PMID 34930323, 2021). "In addition, analysis of the Skrzypczak colorectal dataset indicated the mRNA expression levels of CXCL6 were significantly unregulated in patients with colorectal carcinoma (fold change = 4.156, P = 3.39E-10)." (PMID 34233297, 2021).
lung cancer (8 papers, 2021 to 2026). A malignant neoplasm involving the lung. "Our findings reveal that METTL3 plays an essential role in Cr (VI)-induced carcinogenesis and that the expression of CXCL6 is associated with lung cancer development." (PMID 41362669, 2026). "In this study, we also demonstrated that METTL3 regulates the expression of CXCL6, which is associated with lung cancer development." (PMID 41362669, 2026). "From our literature review, lung cancer appears to be the only cancer with the investigation of miRNA and CXCL6 regarding CXCR1 and CSCs." (PMID 36831112, 2023). "CXCL6 induced proliferation and metastasis of lung cancer cell lines was confirmed in other studies, and the role of CXCL6 in the TME of NSCLC is unclear." (PMID 34637697, 2021). "The other miRNA of interest regarding CXCL6 and lung cancer is miRNA-101-5p." (PMID 36831112, 2023).
non-small cell lung carcinoma (7 papers, 2006 to 2024). A group of at least three distinct histological types of lung cancer, including non-small cell squamous cell carcinoma, adenocarcinoma, and large cell carcinoma. "Besides, miR-515-5p impedes tumor cells by targeting CXCL6 in non-small cell lung cancer (NSCLC)." (PMID 33413401, 2021).
rheumatoid arthritis (7 papers, 2016 to 2024). A chronic, systemic autoimmune disorder characterized by inflammation in the synovial membranes and articular surfaces. "The Enrichr pathway assignment analysis (KEGG 2021 Human database) additionally revealed enrichment of chemokine encoding genes (CXCL1, CXCL2, CXCL3, CXCL6, CXCL5, CXCL8, CCL2) which were aligned to several pathways like amoebiasis and rheumatoid arthritis." (PMID 35646693, 2022). "The chemokines CXCL1 and CXCL6 are chemotactic cytokines involved in various pathological processes including inflammatory diseases, and it has been shown that both CXCL1, CXCL6, and SEMA7A are involved in the inflammatory response in joint-related diseases such as rheumatoid arthritis." (PMID 32434555, 2020). "Elevated expression of the CXCL6 gene was observed in OA chondrocytes and FLS-rheumatoid arthritis (FLS-RA) cells stimulated in vitro with IL-1β and resistin (adipokine), respectively." (PMID 36233118, 2022).
cervical cancer (5 papers, 2021 to 2023). A primary or metastatic malignant neoplasm involving the cervix. "Finally, the mRNA level of CXCL6 was negatively associated with the miR-101-5p level in cervical cancer tissue." (PMID 34833360, 2021). "CXCL6 is the target protein of miR-101-5p in cervical cancer and over-regulation of miR-101-5p reduced the tumor growth of cervical cancer cell in vivo." (PMID 34833360, 2021). "By inhibiting CXCL6, MicroRNA-101-5p inhibits the growth and metastasis of cervical cancer cells." (PMID 34833360, 2021). "Epiregulin was positively correlated with most chemokines, such as CXCL1, CXCL2, CXCL3, CXCL5, CXCL6, CXCL8, and CCL20, in most types of cancer, including cervical cancer." (PMID 37020674, 2023). "This study revealed that the presence of HPV16 and 18 oncogenes significantly alter the expression of CCL28, CXCL1, CXCL2, CXCL3, CXCL6, CXCL8, CXCL10, and CXCL11; overexpression of those chemokines was also confirmed in cervical cancer biopsies." (PMID 37893029, 2023).
gastric cancer (5 papers, 2022 to 2025). A primary or metastatic malignant neoplasm involving the stomach. "We identified 12 driver genes potentially involved in the gastritis-to-cancer transformation, with CHI3L1, MMP12, CXCL6, IDO1, and CCL20 emerging as the top five genes via a early gastric cancer diagnostic model." (PMID 40108688, 2025). "CXCL3 and CXCL6 were significantly upregulated in gastric cancer tissues compared with normal tissues using the UALCAN database and RT-qPCR." (PMID 37161430, 2023). "Immunohistochemical screening of human gastric cancer specimens revealed that CXCL6 was frequently expressed in cancer cells at a high level, while staining in fibroblastic cells was observed in limited cases." (PMID 34379869, 2022).
mastitis (5 papers, 2016 to 2022). Inflammation of breast tissue during lactation or postpartum due to an obstructed duct or infection. "Considering the specificity of biomarkers for rapid detection, IL8RB, CXCL6, and MMP9 were identified as the most potential biomarker for E. coli mastitis." (PMID 31921295, 2019). "Results from previous studies indicated that bovine mammary epithelial cells can express CXCL6 (also called GCP2) and CCL8 (also called MCP2) in response to certain bacterial cell components during the simulation course of mastitis in vitro." (PMID 27478614, 2016). "The CXCL6 usually significantly altered the expression level at bMECs after infection but not at mammary tissues with mastitis." (PMID 35812870, 2022).
pulmonary fibrosis (5 papers, 2020 to 2023). Chronic progressive interstitial lung disorder characterized by the replacement of the lung tissue by connective tissue, leading to progressive dyspnea, respiratory failure, or right heart failure. "CXCL6 is also linked to pulmonary fibrosis and cystic fibrosis; it is upregulated in these conditions and its inhibition could have a beneficial effect on remodeling in asthmatic lungs." (PMID 37386145, 2023). "CXCL6 antibody neutralization attenuates early lung inflammation and prevents pulmonary fibrosis after bleomycin administration." (PMID 37122736, 2023). "CXCL6 contributes to experimental pulmonary fibrosis induced with bleomycin in mice by PI3K/Akt/GSK-3β/Snail signaling." (PMID 32132577, 2020). "The inflammatory response induced by CXCL6 promoted the progression of pulmonary fibrosis." (PMID 37122736, 2023). "Additionally, it’s found that CXCL6 can hasten the course of lung fibrosis, and its concentration markedly increases in patients diagnosed with idiopathic pulmonary fibrosis." (PMID 37509721, 2023). "CXCL6 and CXCL16 were particularly noteworthy because of their increased concentrations in NPAs from hRSV-positive children and their association with several chronic lung pathologies, such as idiopathic pulmonary fibrosis (IPF), CF, chronic rhinosinusitis (CRS) and asthma." (PMID 32075873, 2020).
renal fibrosis (5 papers, 2023 to 2024). A final common manifestation of a wide variety of chronic kidney diseases characterized by glomerulosclerosis and tubulointerstitial fibrosis. "Additionally, CXCL6 can accelerate the development of renal fibrosis through the JAK/STAT3 signaling pathway." (PMID 38168591, 2024). "CXCL6 was upregulated in kidney tissues and blood of DKD humans and rats, and renal fibrosis and renal injury were obvious in the kidneys of these models." (PMID 37635867, 2023). "Through the JAK/STAT pathway, CXCL6 may stimulate the production of TGF-β1, collagen I, collage III, MMP2, and MMP9, thereby speeding the renal fibrosis process in DKD SD rats." (PMID 37635867, 2023).
asthma (4 papers, 2013 to 2024). "Other chemokines that appear to be induced by Alternaria are CXCL1 and CXCL6, potent neutrophil granulocyte chemoattractants that have been found in the early phase of experimental and clinical asthma and in the inflamed airway mucosa in COPD patients." (PMID 23882263, 2013). "Few studies of human disease have investigated the biological role of CXCL6; however, ortholog CXCL5/ENA78 is involved in a variety of inflammatory diseases such as ARDS, acute coronary syndromes, inflammatory bowel disease, asthma, and psoriasis, diseases known to have a neutrophil component." (PMID 26617980, 2015).
diabetes (4 papers, 2017 to 2026). "Significant increases in MIG/CXCL6 and IP-10/CXCL10 have been suggested as a causative agent of diabetes in mammals." (PMID 35153741, 2021). "We observed associations between self-reported diabetes and the chemokines previously reported in the literature, including CXCL10 and interleukin-8 (IL-8), as well as identified a number of novel associations such as: CCL19, CCL20, CCL21, CXCL6, and CXCL11." (PMID 28753646, 2017).
esophageal squamous cell carcinoma (4 papers, 2021 to 2023). Esophageal squamous cell carcinoma (ESCC) is a type of esophageal carcinoma (EC) that can affect any part of the esophagus, but is usually located in the upper or middle third. "The growth and metastases of esophageal squamous cell carcinoma cells were promoted by CXCL6 in vivo and in vitro through the activation of the STAT3 pathway." (PMID 37491836, 2023). "CXCL-6 also has pro-proliferative effects including promoting the proliferation, migration, and invasion of esophageal squamous cell carcinoma cells." (PMID 36142285, 2022).
glioma (4 papers, 2020 to 2025). A benign or malignant brain and spinal cord tumor that arises from glial cells (astrocytes, oligodendrocytes, ependymal cells). "Neutrophils are recruited to glioma inflammatory regions by chemokines such as CXCL1, CXCL2, CXCL3, CXCL5, CXCL6, IL-8 (CXCL8), and IL-1β, which are secreted by glioma cells." (PMID 41272822, 2025). "In the training cohort, CXCL14 (P value < 0.001), CXCL9 (P value < 0.05), CXCL10 (P value < 0.001), CXCL11 (P value < 0.001), CXCL6 (P value < 0.001), and CXCL1 (P value < 0.001) were enriched in the IDH wide-type gliomas." (PMID 34603309, 2021).
liver cancer (4 papers, 2023 to 2025). An epithelial or non-epithelial malignant neoplasm that arises from the liver. "To determine the functional relevance of this finding, we reanalyzed Hoshida Golub Liver GSE10143 (n = 162) data and demonstrated that the high expression of CXCR2 and CXCL6 was associated with worse overall survival in patients with liver cancer." (PMID 37509721, 2023). "The findings also suggest that the invasive zone may have potential therapeutic targets, including SAAs and CXCL6, allowing for more precise treatment of liver cancers." (PMID 37337030, 2023). "The higher positive expression of CD8A and CXCL6 was found in both LIHC tissues and most human liver cancer cell lines." (PMID 37325556, 2023). "RT-qPCR results indicated higher positive expression of CD8A and CXCL6 in both LIHC tissues and most human liver cancer cell lines." (PMID 37325556, 2023). "Through the experiment, it was found out that CD8A and CXCL6 showed higher positive expression in both LIHC tissues and most human liver cancer cell lines, which implied that both PRDEGs might be potential biomarkers for the diagnosis and treatment of LIHC." (PMID 37325556, 2023). "Using a cell coculture system (Transwell), we cocultured Huh7 liver cancer cells and THP-1 monocytes with and without CXCL6/CXCR2 small interfering RNA for 72 h." (PMID 37509721, 2023).
pancreatic cancer (4 papers, 2022 to 2025). "Additionally, the higher expression of the human homolog of mouse Cxcl5, CXCL6, and other ligands of CXCR2 (CXCL1 and CXCL2) was also identified in human pancreatic cancer cells after adding AMP." (PMID 37867243, 2023).